CSF1 (colony stimulating factor 1)
Diseases named in the same sentence as CSF1 in open-access papers (continued):
Sharing a sentence is not in itself a finding about the gene and the disease.
chronic lymphocytic thyroiditis (1 paper, 2022). "Moreover, CSF1 induces pro-tumoral M2 macrophage polarization through binding to CSF1R, whereas CXCL9 and CXCL10 are involved in T-cell recruitment manifested as chronic lymphocytic thyroiditis, which has been associated with a better prognosis of PTC." (PMID 35515000, 2022).
CNS demyelinating diseases (1 paper, 2024). "Considering the significance of CSF-1 in CNS demyelinating diseases, further validation using comprehensive clinical data is warranted to elucidate the relationship between CSF-1 levels and NMOSD." (PMID 38737586, 2024).
cocaine addiction (1 paper, 2025). "Furthermore, the glial modulator and phosphodiesterase 4 (PDE4) inhibitor ibudilast ameliorates cocaine addiction in both humans and animals, and the colony stimulating factor-1 (CSF-1) inhibitor PLX3397 also reduces cocaine-induced behavioural changes by depleting microglia." (PMID 39917617, 2025).
colon adenoma (1 paper, 2018). An adenoma that arises from the colon. "Analyses of colon adenomas indicate that CSF1 may be a key facilitator of macrophage self-renewal." (PMID 29422500, 2018).
colorectal tumors (1 paper, 2022). "Moreover, we demonstrated that CSF1R+ macrophages favored immune suppression mainly by limiting CD8+ T cell infiltration and differentiation, which is compatible with a previous study in CSF1-silenced colorectal tumors that presented increased CD8+ T cell attack." (PMID 35315360, 2022).
cryptococcosis (1 paper, 2020). An acute or chronic, localized or disseminated infection by Cryptococcus neoformans. "In the combined cohort of 319 cases and 399 controls, all 6 CSF1 SNPs remained significantly associated with cryptococcosis susceptibility." (PMID 33269293, 2020). "Meta-analysis of the genotyped CSF1 SNP rs1999713 showed an odds ratio for cryptococcosis susceptibility of 0.53 (95% confidence interval, 0.42–0.66; P = 5.96 × 10−8)." (PMID 33269293, 2020). "Six loci upstream of the colony-stimulating factor 1 (CSF1) gene, encoding macrophage colony-stimulating factor (M-CSF) were associated with susceptibility to cryptococcosis at P < 10–6 and remained significantly associated in a second South African cohort (83 cases; 128 controls)." (PMID 33269293, 2020).
cystic kidney disease (1 paper, 2023). A congenital or acquired kidney disorder characterized by the presence of renal cysts. "Cytokines including CCL2, CSF1 and CX3CL1 are associated with inflammation in cystic kidney diseases." (PMID 36457161, 2023).
delirium (1 paper, 2025). A disorder characterized by confusion; inattentiveness; disorientation; illusions; hallucinations; agitation; and in some instances autonomic nervous system overactivity. "The utility of astrocytic and microglial plasma biomarkers, including chitinase-3-like protein 1, translocator protein (18 kDa), CX3CL1 and CSF1, which are currently being trialled for other disorders should also be explored in the context of delirium." (PMID 39463449, 2025).
demyelination (1 paper, 2025). "In an acute demyelination mouse model, activated astrocytes express multiple ligands, including Cx3cl1, Csf1, Il34, and Gas6, which act on both homeostatic and activated microglia, thereby potentially mediating microglial activation, recruitment, and enhancing their phagocytic activity." (PMID 40292254, 2025).
dentinal caries (1 paper, 2017). "Dental pulp fibroblasts from dentinal caries sections immunostained for CSF-1 in about 38% of the teeth, while no immunostaining was observed in sections from non-carious teeth." (PMID 28779164, 2017).
E. coli infection (1 paper, 2020). "It is important to note that administration of the EPS treatment prior to E. coli infection attenuated CSF1 gene expression, logFC of 1.70." (PMID 32234079, 2020). "A plausible anti-inflammatory effect of EPS was observed in this study, as the expression of the IL12B, TNF, CSF1 and CSF3 genes was abated in the cells pretreated before E. coli infection." (PMID 32234079, 2020).
embryonic carcinoma (1 paper, 2018). "To gain further insight into the regulation of CSF1 and CX3CL1 by miR-125b in embryonic carcinoma, we performed miRNA-Seq of miR-125b antagomir-, miR-125b agomir-, and negative control-transfected NCCIT cells." (PMID 30237497, 2018).
endometrial adenocarcinoma (1 paper, 2022). "In the case of EC, CSF-1 and its receptor have been revealed to overexpress in human endometrial adenocarcinoma, and the serum CSF-1 levels in patients with EC were significantly elevated in active or recurrent EC patients." (PMID 35804859, 2022).
fibromyalgia (1 paper, 2025). A chronic disorder of unknown etiology characterized by pain, stiffness, and tenderness in the muscles of neck, shoulders, back, hips, arms, and legs. "IL‐6, CSF‐1 have been highlighted in a previous proteomics study on fibromyalgia." (PMID 41170664, 2025).
Follicular Cyst (1 paper, 2023). Cyst due to the occlusion of the duct of a follicle or small gland. "FGF7 regulated the PPAR signaling pathway (FABP5 and SCD) and the MAPK signaling pathway (FGF1, FGFR2, IL1A, TGFB1, and CSF1) and pathways in cancer (IL7, CD44, SMAD2, and MMP2) may be involved in the formation of follicular cysts." (PMID 38274662, 2023).
follicular lymphoma (1 paper, 2022). Follicular lymphoma is a form of non-Hodgkin lymphoma characterized by a proliferation of B cells whose nodular structure of follicular architecture is preserved. "Colony-stimulating factor-1 (CSF-1) and its receptor CSF-1R have been thoroughly studied in follicular lymphoma, and the results have indicated that macrophages can be a new therapeutic target because CSF-1 is one of the most important recruitment factors for macrophage polarization." (PMID 35875135, 2022).
gallbladder cancer (1 paper, 2023). "For gallbladder cancer, CSF1 and TIE2 but not TRAIL (p=0.15), remained prognostic." (PMID 37404757, 2023).
hemolysis (1 paper, 2023). Disruption of the integrity of the erythrocyte membrane causing release of hemoglobin. "Collectively, these findings suggest that intravascular hemolysis can trigger CSF-1 production and that CSF-1 is a key regulator of PMo numbers in SCD." (PMID 37490346, 2023).
Hepatic steatosis (1 paper, 2021). Steatosis is a term used to denote lipid accumulation within hepatocytes. "We recently found that the plasma levels of CSF‐1, OSM, and FGF‐21 are significantly associated with hepatic steatosis (Lovric et␣al, 2018)." (PMID 34694070, 2021).
Herpes simplex virus encephalitis (1 paper, 2022). "For example, the early CSF1-dependent microglial response is essential for efficient control of Herpes simplex virus encephalitis challenge in mice and microglia are implicated in many aspects of physiological myelination and remyelination following injury." (PMID 35333324, 2022).
Hypercortisolism (1 paper, 2020). "Hypercortisolism stimulates the expression of receptor activator of nuclear factor κB ligand (RANK-L) and colony stimulating factor 1 (CSF-1) while decreasing the expression of osteoprotegerin (OPG), the net effect of which is to promote osteoclastogenesis." (PMID 32582784, 2020).
Hyperoxaluria (1 paper, 2023). Increased excretion of oxalates in the urine. "In this trial, they found that CSF-1 is mainly secreted from renal tubular epithelium and play an important role in M2 macrophages proliferation and in extension suppression of hyperoxaluria." (PMID 37093310, 2023). "However, they found that AR increase miRNA expression which inhibit CSF-1 resulting in M2 macrophages inhibition and promoting hyperoxaluria." (PMID 37093310, 2023).
intestinal tumors (1 paper, 2020). "However, data from the murine ApcMin tumor model suggest that CSF-1 supports maintenance and self-renewal of pro-tumorigenic macrophages in intestinal tumors, implicating rather tumor-promoting functions of CSF-1 in this mouse model." (PMID 32987848, 2020).
intrahepatic cholangiocarcinoma (1 paper, 2023). A carcinoma that arises from the intrahepatic bile duct epithelium in any site of the intrahepatic biliary tree. "TRAIL and CSF1, prognostic factors in intrahepatic cholangiocarcinoma, showed marked differences in expression and activity between intra- and peritumoral immune cells." (PMID 37404757, 2023).
Kawasaki disease (1 paper, 2021). A rare inflammatory disease characterized by an acute febrile, systemic, self-limiting, medium-vessel vasculitis primarily affecting children. "There is an essential role for CSF1 and granulocyte/macrophage colony-stimulating factor (GM-CSF) in the pathogenesis of Kawasaki disease." (PMID 33692975, 2021).
kidney damage (1 paper, 2025). "Under these inflammatory conditions, TECs also become a primary source of colony-stimulating factor-1 (CSF-1), which promotes macrophage survival, differentiation, and functional polarization, further driving both immune-dependent and independent kidney damage in LN." (PMID 41376645, 2025).
lymph node tumor (1 paper, 2016). "In addition, one study has reported detection of lymphocyte-associated MCSF in human lymph node tumor biopsies, and two others found evidence for Csf1 production in decidual T cells during pregnancy." (PMID 27923070, 2016).
lymphedema (1 paper, 2022). Excess fluid collection in tissues, causing swelling. "The expression of CSF1 in ASCs was significantly higher in lymphedema than in the healthy condition, reflecting enhanced signals broadcast by ASCs under the diseased condition." (PMID 35725971, 2022). "Since the expression of CSF1 in ASCs was even significantly higher in lymphedema than in healthy controls, we reason that the mechanism underlying the depletion of macrophages, especially for the LYVE1+ macrophages, may not be due to pathological changes in ASCs." (PMID 35725971, 2022).
male infertility (1 paper, 2021). The inability of the male to effect fertilization of an ovum after a specified period of unprotected intercourse. "Thus, it is possible to suggest that CSF-1 system, as a testicular paracrine/autocrine system, is involved in the development of different stages of spermatogenesis and may be used in the development of future therapeutic strategies for treatment of male infertility." (PMID 33652607, 2021).
mast cell tumors (1 paper, 2022). "Toceranib targets receptor tyrosine kinases, including C-KIT, VEGFR-2, PDGFa/b, and CSF-1 (colony stimulating factor–1) and is used as a first-line treatment for dogs with mast cell tumors." (PMID 36012610, 2022).
myelofibrosis (1 paper, 2024). A partial or complete replacement of the bone marrow stroma by fibrous tissue. "The per cell expression of NSF, in particular Cxcl12 and Csf1, was markedly decreased in myelofibrosis vs. control bone marrow MSCs but increased in fibroblasts at transcript level." (PMID 39383242, 2024).
Nasu-Hakola disease (1 paper, 2020). "The more severe phenotype, which was associated with bone malformation, bears similarity to TREM2-associated Nasu-Hakola disease and suggests CSF-1 and TREM2 act on convergent pathways." (PMID 32430064, 2020).
neovascular age-related macular degeneration (1 paper, 2024). "Moreover, in neovascular age-related macular degeneration, under hypoxic conditions, HIF-1α upregulates the expression of CSF-1 in choroidal ECs and CSF-1 expression is mediated by HIF-1α binding to the hypoxia response element in the CSF-1 promoter." (PMID 39457693, 2024).
non-proliferative diabetic retinopathy (1 paper, 2025). Early stage diabetic retinopathy, characterized by the absence of neovascularisation of the retina. "Interestingly, a CSF-1-dependent microgliosis has also been demonstrated in a streptozotocin-induced model of non-proliferative diabetic retinopathy, which does not develop intra-retinal revascularization or neovascularization." (PMID 40087728, 2025).
osteonecrosis (1 paper, 2025). A none disease characterized by death of bone tissue due to a lack of blood supply. "On the other hand, 3 cytokines showed a negative causal effect on osteonecrosis, suggesting a decreased risk: MCP-4 (IVW OR = 0.81, 95% CI = 0.67–0.99, P = .038), IL-10RB (IVW OR = 0.84, 95% CI = 0.699–0.999, P = .049), and CSF1 (IVW OR = 0.72, 95% CI = 0.54–0.96, P = .026)." (PMID 40760551, 2025).
ovarian adenocarcinoma (1 paper, 2014). An adenocarcinoma that arises from the ovary. "High expression of CSF-1, or c-fms and/or abnormal levels of M-CSF were also reported in chronic inflammatory conditions and ovarian adenocarcinoma, malignant germ cells of ovarian, lung, liver and other cancers at various stages of the disease." (PMID 24473090, 2014).
ovarian failure (1 paper, 2023). "Our finding that eliminating Csf1 allows for sustained maintenance of oocytes and prevents ovarian failure due to genetic factors raises the possibility that blocking Csf1 might be a strategy to preserve ovarian health during chemotherapy." (PMID 37992158, 2023).
ovary (1 paper, 2020). "Overexpression of CSF‐1 has been reported in cancers of ovary, breast and liver, and is inversely related to prognosis and survival rate in these patients." (PMID 31994318, 2020).
pleural mesothelioma (1 paper, 2022). A neoplasm that arises from the mesothelial cells of the pleura. "Recent study reports that EZH2 inhibitor EPZ-6438 triggers malignant pleural mesothelioma cells to express high level of different monocytes chemoattractants, including CCL2 and CSF1, which lead to increased monocytes recruitment in tumor spheroids as well as M2 TAMs differentiation." (PMID 36038549, 2022).
prostate (1 paper, 2023). "While the specific role of ATF3 (activating transcription factor 3) in the suppression of PCa with PTEN (phosphatase and tensin homolog) dysfunction is meanwhile well known, the tumor suppressor function of IGF1, CXCL10, HIF1A, CXCL8, and CSF1 in prostate carcinogenesis remains to be elucidated." (PMID 36321189, 2023).
renal fibrosis (1 paper, 2025). A final common manifestation of a wide variety of chronic kidney diseases characterized by glomerulosclerosis and tubulointerstitial fibrosis. "These CD38hi macrophages, derived from resident macrophages via Csf1 signaling, secrete the NAD-depleting enzyme CD38, inducing senescence in renal tubular cells and promoting chronic inflammation and renal fibrosis." (PMID 40349105, 2025).
Sjögren’s syndrome (1 paper, 2016). "There is an increasing interest in IL-34 and CSF-1, where IL-34 overexpression was observed in inflammatory conditions including Sjögren’s syndrome, whereas overexpression of IL-34 and CSF-1 was reported for RA and IBD." (PMID 27898738, 2016).
Sleep apnea (1 paper, 2025). An intermittent cessation of airflow at the mouth and nose during sleep is known as sleep apnea. "Further studies are needed to determine whether sleep apnea influences these CSF1 levels and the associated microgliosis and how these parameters compare between proliferative and non-proliferative DR." (PMID 40087728, 2025).
synovial neoplasm (1 paper, 2026). "DTGCT is a benign synovial neoplasm driven by a chromosomal translocation t (1:2) (p13; q37), resulting in fusion of the COL6A3 promoter region with the CSF1 gene, leading to CSF1 overexpression." (PMID 41523664, 2026).
tauopathy (1 paper, 2018). Neurodegenerative disorders involving deposition of abnormal tau protein isoforms (tau proteins) in neurons and glial cells in the brain. "Interestingly, the expression changes of genes such as Gfap, Csf1, Prnp, C4b and Trem2, identified with 2 m Tau hippocampi (GSE107183) have been observed at symptomatic stages in the same rTg4510 tauopathy model in other studies." (PMID 29915328, 2018).
teratoma (1 paper, 2021). A non-seminomatous germ cell tumor characterized by the presence of various tissues which correspond to the different germinal layers (endoderm, mesoderm, and ectoderm). "Although the amount of their production from the teratoma is unclear, these factors have been reported to circulate in wt serum on the order of ng/mL (Prl2c, resistin, insulin growth factor 2, angiopoietin, C1qtnf3, Postn, IGFBPs, PPBP), and pg/mL (colony-stimulating factor 1)." (PMID 33888706, 2021).
thoracic cancer (1 paper, 2025). A primary or metastatic malignant neoplasm affecting the tissues of the thorax. "Previous studies from our lab showed that thoracic cancer cell lines could mediate the M2-like polarization of monocytes in 2D and 3D cocultures, involving tumor-secreted cues including the M-CSF/CSF1." (PMID 41310721, 2025).
thyroid (1 paper, 2020). "The study of the tumor microenvironment (TME) showed that thyroid tumoral tissues overexpress CSF-1 and CCL-2 that attract tumor associated macrophages (TAMs)." (PMID 32668761, 2020).
thyroid tumor (1 paper, 2019). A benign or malignant neoplasm affecting the thyroid gland. "We found that proliferating and senescent thyrocytes, the immortalized cell line Nthy, and four of nine thyroid tumor cell lines induced macrophage maturation; all of them produced CSF-1, the major growth and differentiation factor for monocytes." (PMID 31113465, 2019).
Upper Tract Urothelial Carcinomas (1 paper, 2019). "However, the precise role of CSF-1 in upper tract urothelial carcinomas (UTUC) has not been studied." (PMID 31565097, 2019).
uveitis (1 paper, 2020). An inflammatory process affecting a part of or the entire uvea. "Further experiments such as using CSF-1 deficient/overexpressed animals or using CSF-1 receptor antagonist in the experimental uveitis are needed to confirm whether CSF-1 is an effective target for modulating uveitis." (PMID 32671118, 2020). "CSF-1 is expected to be a new therapeutic target for uveitis." (PMID 32671118, 2020). "Therefore, the next step is to investigate whether CSF-1 is involved in endotoxin tolerance in uveitis and its relationship with TLR4 and NF-κB p65." (PMID 32671118, 2020). "It is not clear whether downregulated CSF-1 is involved in reducing uveitis, which this study intends to explore." (PMID 32671118, 2020). "Therefore, this study attempted to investigate whether CSF-1 and LRR-1 are involved in endotoxin tolerance in uveitis through the TLR4 pathway and their exact mechanisms." (PMID 32671118, 2020).
viral myocarditis (1 paper, 2018). Myocarditis that is caused by an infection with a viral agent. "Since we found reduced mobilization of monocytes/macrophages in siCSF-1-treated mice during CVB3 infection, this mouse model allowed us to delineate the pathophysiological role of CSF-1 production particularly by monocytes/macrophages during viral myocarditis." (PMID 30349538, 2018). "We performed immunohistochemical stains to evaluate CSF-1 abundance during viral myocarditis." (PMID 30349538, 2018). "We conclude that attenuated innate immune cell mobilization and hampered CSF-1-driven differentiation of innate myeloid cells in siCSF-1-treated mice directly suppresses cytotoxicity induced by cytokine production and/or infiltration with lymphocytes in viral myocarditis." (PMID 30349538, 2018).